RPL15 (ribosomal protein L15)
Description:
Component of the large ribosomal subunit. The ribosome is a large ribonucleoprotein complex responsible for the synthesis of proteins in the cell.
Synonyms: EC45; RPL10; RPLY10; RPYL10; L15; eL15; DBA12
Tractability: Small molecule: an approved drug acts on it; a structure with a bound ligand is known; a high-quality ligand is known. PROTAC: UniProt records ubiquitination sites on it; ubiquitination databases record sites on it; its protein half-life has been measured; a small molecule that binds it is known. Other modalities: a drug acting on it is in phase 2 or 3 trials.
Target class: Other cytosolic protein
Gene: Protein-coding gene on chromosome 3 (23,916,591 to 23,924,374, forward strand). Ensembl gene ENSG00000174748.
Subcellular location: Cytoplasm
Pathways (Reactome):
Metabolism of proteins: Eukaryotic Translation Termination; Formation of a pool of free 40S subunits; GTP hydrolysis and joining of the 60S ribosomal subunit; L13a-mediated translational silencing of Ceruloplasmin expression; PELO:HBS1L and ABCE1 dissociate a ribosome on a non-stop mRNA; Peptide chain elongation; Ribosome Quality Control (RQC) complex extracts and degrades nascent peptide; SRP-dependent cotranslational protein targeting to membrane; ZNF598 and the Ribosome-associated Quality Trigger (RQT) complex dissociate a ribosome stalled on a no-go mRNA
Metabolism of RNA: Major pathway of rRNA processing in the nucleolus and cytosol; Nonsense Mediated Decay (NMD) enhanced by the Exon Junction Complex (EJC); Nonsense Mediated Decay (NMD) independent of the Exon Junction Complex (EJC)
Cellular responses to stimuli: Response of EIF2AK4 (GCN2) to amino acid deficiency
Developmental Biology: Regulation of expression of SLITs and ROBOs
Disease: Viral mRNA Translation
Metabolism: Selenocysteine synthesis
Gene Ontology:
Molecular function: cadherin binding; protein binding; RNA binding; structural constituent of ribosome
Biological process: cytoplasmic translation; negative regulation of myoblast fusion; spermatogenesis; striated muscle contraction; translation; response to ethanol
Cellular component: cytoplasm; cytosolic large ribosomal subunit; cytosolic ribosome; nucleus; cytosol; ribosome; A band; ribosomal subunit; synapse
Genetic constraint (gnomAD): Loss-of-function variants: 0 observed, 22.54 expected, observed/expected ratio (o/e) 0, 90% interval 0 to 0.13. The upper end of that interval is the gene's LOEUF score, 0.13, which puts it in group 1 of 6, group 1 being the genes least tolerant of losing a copy. Missense variants: 154 observed, 244.76 expected, observed/expected ratio (o/e) 0.63, 90% interval 0.55 to 0.72. Synonymous variants: 94 observed, 85.81 expected, observed/expected ratio (o/e) 1.1, 90% interval 0.93 to 1.3.
Homologues: Orthologues: chimpanzee RPL15 (100% identical), macaque RPL15 (100% identical), mouse Rpl15 (100% identical), pig RPL15 (100% identical), rat Rpl15 (100% identical), zebrafish rpl15 (96% identical), tropical clawed frog rpl15 (94% identical), rabbit RPL15 (77% identical), Caenorhabditis elegans rpl-15 (76% identical), Drosophila melanogaster RpL15 (74% identical).
Diseases named in the same sentence as RPL15 in open-access papers:
RPL15 is named in the same sentence as 40 diseases in open-access papers, as found by Europe PMC text mining. Sharing a sentence is not in itself a finding about the gene and the disease. The quoted sentences say what the papers report.
breast carcinoma (21 papers, 2015 to 2024). "Deregulation of RPL15 expression enhances the translation of RPs and E2F pathway proteins to promote breast cancer metastasis, while mutations in RPs, including RPL10 and RPS15, also provide a potential oncogenic mechanism." (PMID 37264021, 2023). "For example, deregulation of ribosomal protein synthesis via RPL15, and in turn protein translation, have been reported to be associated with breast cancer metastasis." (PMID 37958436, 2023). "Overexpression of eL15/RPL15 in circulating tumor cells promoted breast cancer metastasis by selectively upregulating the translation of proteins that promote cell proliferation." (PMID 37047306, 2023). "Knocking out RPL15 using CRISPR technology significantly weakened lung metastasis in breast cancer circulating tumor cells in mouse models, and with RPL15 overexpression, breast cancer circulating tumor cells had stronger lung and ovarian metastasis ability." (PMID 36004921, 2022). "Ribosomal protein RPL15 upregulates the expression of cell cycle mediators and facilitates breast cancer metastasis in vivo." (PMID 36050449, 2022). "RPL15 was related to the prognosis of different cancers: glioma, breast cancers, gastric cancer, leukemia and pancreatic ductal adenocarcinoma." (PMID 34727106, 2021). "An in vivo genome-wide CRISPR activation screen has identified the overexpression of RPL15 in breast cancer patient-derived circulating tumor cells in mice." (PMID 34873618, 2021). "Among the ribosome protein genes, the RPL27A and RPL15 genes were upregulated in metastatic cancer cells with significant differences, which was consistent with the data in mouse breast cancer models." (PMID 34497807, 2021). "RPL15 (eL15), a component of the large ribosomal subunit, increases the translation rate of other RPs and cell cycle regulators, leading to breast cancer cells metastatic growth in multiple organs." (PMID 36046433, 2021). "The high levels of RL15 are linked to an increase in metastatic growth and enhancement of translation of other RPs and cell cycle regulators suggesting the role of RPL15 in breast cancer metastasis." (PMID 34873618, 2021). "The causal tumorigenic effect of overexpressed RPL15 and RPL35 was similarly demonstrated in immune-deficient NOD SCID mouse models of human breast cancer metastasis to the lung and ovary." (PMID 33120992, 2020). "This study suggests that increased protein synthesis induced by RPL15/RPL35 high expression in CTCs contributes to breast cancer progression." (PMID 33120992, 2020). "While RPL15 was identified during an in vivo genome-wide CRISPR activation screen to identify genes in breast cancer patient-derived CTCs that promote their distant metastasis in mice, the latter was trained on a cohort of normal vs primary tumor and whole blood from patients." (PMID 38312224, 2024). "Interestingly, overexpressed RPs have also been reported in cancers, such as eL15/RPL15 in breast cancer, promoting cell cycle and metastasis, and in melanoma, reducing stress signalling and anti-tumorigenic response." (PMID 37606454, 2023). "RPL15 overexpression could influence the cell proliferation and metastasis of gastric cancer and breast cancer." (PMID 38155938, 2023). "For example, RPL15 is upregulated in circulating tumor cells in breast cancer." (PMID 37062845, 2023). "Overexpression of ribosomal protein RPL15 promotes breast cancer metastasis." (PMID 35387667, 2022). "However, a recent report in mice argued that over-expression of RPL15 (eL15) not only enhanced translation of other genes, including cell cycle regulators, but also promoted distant metastases in mice with breast cancer." (PMID 32810425, 2020). "The current results may be particularly interesting in view of those recently published by Ebright at al,41 wherein RPL15 overexpression promoted metastatic breast cancer growth and circulating tumor cells from patients with breast cancer displayed ribosome and protein synthesis signatures." (PMID 33705753, 2021).
breast carcinoma (continued). "Importantly, this study also showed that in metastatic breast cancer patients expressing sex hormone receptors, characterization of CTCs with high RPL15/RPL35 expression could discriminate patients with the worse overall survival." (PMID 33120992, 2020). "As RPL15 was a reported pro-metastasis gene in breast cancer, we next checked the transcript colocalization of RPL27A with RPL15 in primary, metastatic, and integrated data." (PMID 34497807, 2021). "For example, upregulation of RPL15 gene expression in breast cancer promotes massive metastasis and triggers enhanced translation of other ribosomal proteins, while inhibition of RPL27A hampers dissemination and invasive potential of breast cancer cells." (PMID 37958436, 2023). "While there is no research paper reporting the role of RPL15 in breast cancer, one study suggested the methylation of RPL15 may be involved in cancer development." (PMID 31874600, 2019).
gastric cancer (13 papers, 2006 to 2023). A primary or metastatic malignant neoplasm involving the stomach. "The overexpression of RPL15 in gastric cancer is associated with tumor cell proliferation." (PMID 36838813, 2023). "The expression of RPL15 varied with the type of cancer, and it was highly expressed in esophageal cancer, gastric cancer, hepatocellular carcinoma, and colon cancer, but lowly expressed in cutaneous squamous cell carcinoma and pancreatic ductal adenocarcinoma." (PMID 37968618, 2023). "In gastric cancer cells, the interaction of RPL15 with the interferon-inducible protein p56 contributes to cell growth regulation." (PMID 36838813, 2023). "While RPL15 was downregulated in cutaneous squamous cell carcinoma and pancreatic ductal adenocarcinoma, it was markedly upregulated in gastric cancer and colon cancer tissues." (PMID 34434692, 2021). "Expression levels of RPL15 were examined by western blot in the gastric cancer and adjacent normal tissues taken from 12 patients." (PMID 16608517, 2006). "We further compared the relative RPL15 expression level in five different gastric cancer cell lines, i.e., AGS, MKN45, MKN28, SGC7901, and KATOIII, with that of the normal gastric cell line GES-1." (PMID 16608517, 2006). "Again, RPL15 was found expressed at a higher level in all five gastric cancer cell lines than in GES-1 cells." (PMID 16608517, 2006). "The RPL15 staining in gastric cancer cells was consistently stronger than those of the NG and NT samples with an average score 6.3 ± 2.90 (p < 0.01)." (PMID 16608517, 2006). "We investigated the expression of ribosomal protein L15 in gastric cancer and the effect of RPL15 on proliferation of gastric cancer." (PMID 16608517, 2006). "To further analyze the involvement of RPL15 in gastric cancer malignant phenotype, we took advantage of siRNA technology." (PMID 16608517, 2006). "In the present study, for the first time we reported that RPL15 was highly expressed in gastric cancer tissues and cell lines, indicating that RPL15 serve as a potential marker for diagnosis of gastric cancer." (PMID 16608517, 2006). "RPL15 was also highly expressed in gastric cancer cell lines AGS, MKN45, MKN28, SGC7901 and KATOIII." (PMID 16608517, 2006). "In our previous study of microarray, ribosomal protein L15 (RPL15) was identified as an upregulated gene in gastric cancer." (PMID 16608517, 2006). "In this context, siRNA-targeting RPL15 was shown to reduce the growth rate of gastric cancer cells." (PMID 36838813, 2023). "Moreover, circular RNA ribosomal protein L15 (circ-RPL15) facilitates gastric cancer progression through inhibiting miR-502-3p." (PMID 36755807, 2023). "RPL15 was highly expressed in gastric cancer cell lines, and interference with the expression of RPL15 could inhibit gastric cancer cell growth." (PMID 35410346, 2022). "The expression of RPL15 was upregulated in gastric cancer tissues and cell lines." (PMID 33584809, 2020). "The effect of RPL15 on the growth of gastric cancer cell line SGC7901 was also investigated." (PMID 16608517, 2006). "RPL15 promotes cell proliferation and may be a potential target for anticancer therapy of gastric cancer." (PMID 16608517, 2006). "It was found that the expression of RPL15 was markedly up-regulated in gastric cancer tissues." (PMID 16608517, 2006). "In the present study, we demonstrated that inhibition of RPL15 expression could suppress the proliferation of gastric cancer by in vitro and in vivo assay." (PMID 16608517, 2006). "So it is interesting to see whether RPL15 is really highly expressed in gastric cancer and the effect of RPL15 on the malignant phenotype of gastric cancer." (PMID 16608517, 2006). "RPL15 is highly expressed in gastric cancer tissues and cell lines." (PMID 16608517, 2006). "Besides, circ-RPL15 promotes gastric cancer progression by suppressing miR-502-3p." (PMID 36755807, 2023). "So RPL15 may be a potential target for anticancer therapy of gastric cancer." (PMID 16608517, 2006).
gastric cancer (continued). "Many RPs are found affected in gastric cancer (GC) including RPS13, RPL23, RPS27, RPL6, RPL13 and RPL15." (PMID 34873618, 2021). "Recently, more and more RPs were found dysregulated in tumors, such as overexpression of RPL15 in esophageal cancer and high-expression of RPL6 in human gastric cancer cell." (PMID 31565098, 2019). "Western blot demonstrated that neither expression of Cyclin D1 nor Cyclin B1 were influenced by ectopic expression of RPL15, indicating there might be other molecules mediating the promoting effect of RPL15 on cell proliferation of gastric cancer." (PMID 16608517, 2006).
colon cancer (5 papers, 2019 to 2023). "Depletion of 60 S ribosomal protein L5 (RPL15) caused ribosomal stress, resulting in apoptosis in colon cancer cells." (PMID 33499187, 2021). "We find that RPL15 is overexpressed in colon cancer cells and tissues, and the expression of RPL15 is closely associated with colon cancer carcinogenesis." (PMID 31523176, 2019). "RPL15 was upregulated in colon cancer tissue and closely associated with colon cancer progression." (PMID 31523176, 2019). "Furthermore, the expression level of RPL15 was associated with colon cancer progression." (PMID 31523176, 2019). "RPL15 is involved in human colon carcinogenesis and is viewed as a potential target for colon cancer therapy." (PMID 36838813, 2023). "We found that RPL15 was overexpressed in colon cancer cell lines and cancer tissue, and elevated expression of RPL15 in colon cancer tissues was closely correlated with clinicopathological characteristics in patients." (PMID 31523176, 2019). "Our results reveal that RPL15 is remarkably upregulated in human primary colon cancer tissues and cultured cell lines when compared with paired non-cancerous tissues and non-transformed epithelium cells." (PMID 31523176, 2019). "Elevated expression of RPL15 in colon cancer tissues is closely correlated with clinicopathological characteristics in patients." (PMID 31523176, 2019). "To investigate the critical role of RPL15 in colon carcinogenesis, we first detected the expression of RPL15 in four colon cancer cell lines using western blot." (PMID 31523176, 2019). "Our results showed that RPL15 was overexpressed in colon cancer tissue and its expression was associated with the progression of colon cancer, we next sought to detect the biological function of RPL15 in colon cancer." (PMID 31523176, 2019). "To date, little is known about the role of RPL15 in colon cancer." (PMID 31523176, 2019). "In this study, we studied the role of RPL15 in colon cancer carcinogenesis." (PMID 31523176, 2019). "However, the mechanisms by which RPL15 depletion resulted in specific apoptosis in colon cancer cells are unclear and need to further investigate." (PMID 31523176, 2019). "Depletion of RPL15 causes ribosomal stress, resulting in a G1-G1/S cell cycle arrest in non-transformed human epithelium cells, but apoptosis in colon cancer cells." (PMID 31523176, 2019). "Together, these results indicate that RPL15 is involved in human colon carcinogenesis and might be a potential clinical biomarker and/or target for colon cancer therapy." (PMID 31523176, 2019). "Furthermore, RPL15 dependent ribosome stress induced specific cell apoptosis in colon cancer cells." (PMID 31523176, 2019). "We examined expression levels of RPL15 in public available human cancer microarray studies using the ONCOMINE database analysis, and the result revealed that RPL15 was upregulated in colon cancer tissues when compared with normal tissues." (PMID 31523176, 2019). "Therefore, RPL15 could be a prospective target for therapy of colon cancer." (PMID 31523176, 2019). "Subsequently, we collected 25 pairs of colon cancer tissue and corresponding adjacent non-cancerous tissue and evaluated the RPL15 expression using immunohistochemistry (IHC)." (PMID 31523176, 2019). "In comparison with a non-transformed epithelial cell line (RPE1), RPL15 protein expression was upregulated in all four colon cancer cell lines (LoVo, SW480, SW620 and HCT116)." (PMID 31523176, 2019). "Here, we demonstrated that the expression of RPL15 in colon cancer tissues was higher than that in adjacent normal tissues." (PMID 31523176, 2019). "We found that 56.5% (13 of 25) colon cancer tissue showed a higher level of RPL15 compared with the corresponding adjacent non-cancerous tissue." (PMID 31523176, 2019). "Furthermore, we demonstrate that depletion of RPL15 induces apoptosis in colon cancer cells, but cell cycle arrest in non-transformed RPE1 cells." (PMID 31523176, 2019).
colon cancer (continued). "We further demonstrated that RPL15 dependent ribosome stress resulted in cell cycle arrest at G1-G1/S phase in non-transformed RPE1 cells, but apoptosis in colon cancer HCT116 cells." (PMID 31523176, 2019). "Human colon cancer cell line, HCT116, and a non-transformed epithelial cell line, RPE1, were transiently transfected with RPL15 siRNAs or NS siRNA." (PMID 31523176, 2019). "Depletion of RPL15, in contrast to non-transformed RPE1 cells, resulted in specific apoptosis in colon cancer cells." (PMID 31523176, 2019).
pancreatic ductal adenocarcinoma (5 papers, 2015 to 2023). An infiltrating adenocarcinoma that arises from the epithelial cells of the pancreas. "Decreased expression of rpL15 may serve as a prognostic marker in pancreatic ductal adenocarcinoma and was significantly associated with poor overall survival." (PMID 27924828, 2016).
Diamond-Blackfan anemia (4 papers, 2015 to 2023). A congenital aregenerative and often macrocytic anemia with erythroblastopenia. "For example, the genotypability of genes RPL15 and RPS26 (associated with the bone marrow disorder Diamond-Blackfan anemia – OMIM 615550,613309 –) improved to 100%, from 49.98% and 47.13%, respectively." (PMID 32523024, 2020). "RPL15 gene deletion was identified in Diamond-Blackfan anemia." (PMID 37968618, 2023). "The patient tested negative for pathogenic variants in genes associated with Diamond-Blackfan anemia: RPS19, RPL5, RPL11, RPS26, RPL35a, and RPL15." (PMID 35774100, 2022).
hepatocellular carcinoma (4 papers, 2022 to 2023). A malignant tumor that arises from hepatocytes. "In this study, we investigated the role of RPL15 in Hepatocellular carcinoma (HCC)." (PMID 35410346, 2022).
leukemia (4 papers, 2020 to 2023). A malignant (clonal) hematologic disorder, involving hematopoietic stem cells and characterized by the presence of primitive or atypical myeloid or lymphoid cells in the bone marrow and the blood. "Pervious study has reported that inhibition of Aurora kinases induced apoptosis and autophagy in leukemia cells via AURKB/p70S6K/RPL15 axis with the involvement of PI3K/Akt/mTOR, AMPK, and p38 MAPK signaling pathways." (PMID 32194783, 2020). "The first one refers to the pan-inhibitor of Aurora kinases danusertib, which has been shown to repress RPL15 signaling, notably negatively regulating the AURKB/p70S6K/RPL15 axis, and the effect leads to cell death (by apoptosis and autophagy) of human leukemia cells." (PMID 36838813, 2023).